BRCA1 (BRCA1 DNA repair associated)
Diseases named in the same sentence as BRCA1 in open-access papers (continued):
Sharing a sentence is not in itself a finding about the gene and the disease.
cancer (continued). "We herein tested the alternative but not mutually exclusive hypothesis that BRCA1 deficiency might cell-autonomously activate RANKL expression to generate cellular states with cancer stem cell (CSC)-like properties." (PMID 28388533, 2017). "Furthermore, factors required for replication fork stability, repair and restart in response to RS, such as the BRCA1 and BRCA2 proteins, SLX4, and FA group members, have all been shown to associated with cancer development when their function is compromised in either human or mouse models." (PMID 28445142, 2017). "In addition, this study identified a significant enrichment of mutations at these sites in the genomes of cancers lacking BRCA1." (PMID 28098815, 2017). "The hypermethylation of the BRCA1 promoter or the loss of function of other genes as ATM, CHEK2, RAD51, BRIP1, and PALB2 belonging at DNA repair machinery, define a specific phenotype with features and behavior similar to BRCA-related cancers, defined as “BRCAness”." (PMID 28055979, 2017). "We tried to explain this cancer association at a molecular level and we discovered that the SNP was associated with a constitutive OGG1 transcriptional down-regulation, which contributed to a higher genome and telomere instability, especially in those individuals harboring mutations in BRCA1." (PMID 29383107, 2017). "Similarly to uptake of BRCA1/2 testing, interest was more consistently related to psychological factors (i.e. perceived risk and greater cancer worry), rather than sociodemographic variables." (PMID 28720130, 2017). "In addition, 39 of 79 (49.4%) patients with BRCA1/2 mutant cancers developed RDR when receiving PARP inhibitor monotherapy, in contrast to 7 of 34 (20.6%) patients with unknown or wildtype BRCA1/2 status (p=0.004)." (PMID 29262651, 2017). "Thus, EEPD1 could be used as a biomarker for treatments that target RAD52 in BRCA1/2 mutant cancers." (PMID 29145865, 2017). "Overall, significantly less OC cases are seen in PALB2 families when compared with BRCA1 and BRCA2 families; therefore, it seems that PALB2 may contribute in a different way than BRCA1 and BRCA2 to cancer predisposition, possibly as a result of PALB2 distinct roles in DDR." (PMID 28858227, 2017). "Stable formation of the heterodimer may be critical for BRCA1 exerting cancer inhibition." (PMID 28055978, 2017). "We have employed relatively simple and sensitive assays to determine the function of BRCA1 variants or mutants in two HDR mechanisms, homologous recombination (HR) and single strand annealing (SSA), and in conferring resistance to cisplatin and olaparib in human cancer cells." (PMID 28398198, 2017). "Given that depleting EEPD1 prevents synthetic lethality of RAD52 repression in BRCA1 mutant cancer cells, potential mechanisms by which cancer cells could become resistant to clinically useful RAD52 inhibitors are by repressing EEPD1 expression or acquiring EEPD1 loss-of-function mutations." (PMID 29145865, 2017). "When this genomic instability is conferred mainly by a single genetic variant such as a BRCA1 mutation, pedigree analysis will reveal a clear autosomal dominant transmission for cancer predisposition, but not all female carriers will develop the disease as penetrance is not absolute." (PMID 28649653, 2017). "However, the molecular mechanism by which RAD52 deficiency causes synthetic lethality of BRCA1/2 mutant cancer cells has not been identified." (PMID 29145865, 2017). "Interestingly, epigenetic defects in BRCA1 have been associated with increased sensitivity to platinum-derived drugs in human cancer, whilst an impairment of at least one BRCA1-interactor protein (SRBC) has been related to increased resistance to these compounds." (PMID 26625211, 2016).
cancer (continued). "For example, a recent study suggests that any BRCA1 allele that permits 20–30% tumor suppressor activity may not confer BRCA-associated cancer risk." (PMID 27313609, 2016). "Alternatively, the incomplete penetrance associated with inherited BRCA1 mutations might reflect the fact that non-genetic modifiers have an important role in determining cancer risk among BRCA1 carriers." (PMID 27259235, 2016). "However, the characteristics of BCSCs from BRCA1-defective cancers are largely unexplored." (PMID 27229859, 2016). "Whether or not cancer-free BRCA1 mutation carriers have lower messenger (m)RNA transcript levels in peripheral blood leukocytes has not been evaluated." (PMID 27534398, 2016). "Mapping BRCA1 pathogenic variants to the BRCT 3-dimensional structure highlights the importance of aa residues implicated in phosphopeptide recognition and provides a strong molecular link between this biochemical function of the BRCA1 protein and cancer predisposition." (PMID 28781887, 2016). "Overall, these studies suggest that all BRCA1 mutations are not equivalent in their tumorigenic potential, and consequently, cancer risk assessment might be mutation specific." (PMID 27534398, 2016). "In addition, the enrichment of FOXC1 and BLBC in BRCA1-mutant tumors may also be explained by development of cancer in FOXC1-expressing luminal progenitor cells, which are enriched in the setting of BRCA1 mutation." (PMID 27708239, 2016). "In this study we have shown how this variant can contribute to increase cancer risk in BRCA1 carriers, by reducing the mRNA OGG1 expression levels, increasing the DNA damage as a consequence of genomic instability generated, and shortening the telomeres in a synergic way with the BRCA1 mutation." (PMID 27015555, 2016). "From the point of view of the proficiency of DNA damage repair, BRCA1-associated TNBCs are not a homogenous group; therefore, they should not be regarded as such when patients with this type of cancer are enrolled in clinical trials of neoadjuvant chemotherapy with cisplatin or PARP inhibitors." (PMID 27626685, 2016). "However, DNA DSB occurs in BRCA1 defective cancer cells which might be either due to the insufficient antioxidant mechanism or a higher quantum of ROS." (PMID 27220670, 2016). "Even though PB acts via multiple pathways to induce cytotoxicity in cancer cells, the major mode of action is the generation of ROS and subsequent DNA damage which could be especially deleterious to BRCA1-defective cancer cells that lack the homologous recombination repair machinery." (PMID 27229859, 2016). "Moreover, postmenopausal status was associated with a nonsignificant increased methylation of BRCA1 promoter in cancer tissue specimens compared with premenopausal females (70.6% versus 29.4%), respectively." (PMID 27413552, 2016). "The in vivo preclinical studies on anti-neoplastic function and toxicological evaluation of PB substantiate that it could be a potential candidate for monotherapy as well as combination therapy with PARP inhibitors or other standard chemotherapeutics for BRCA1-defective cancer treatment." (PMID 27220670, 2016). "In addition, BRCA1/2 testing may have direct implications for patients with other types of cancers, many of which are now being found to have BRCA1/2 involvement." (PMID 27242959, 2016). "Therefore, BRCA1-KO fibroblasts were treated with cancer serum for 2 weeks." (PMID 27179759, 2016).
cancer (continued). "In addition, one of the 9 active compounds, adenosine 5’-monophosphate (A5MP), and also its mimic 5-aminoimidazole-4-carboxamide ribonucleotide (AICAR) 5’ phosphate (ZMP) inhibited RAD52 activity in vivo and exerted synthetic lethality against BRCA1 and BRCA2–mutated carcinomas." (PMID 26784987, 2016). "BRCA1 is a transcription factor involved in numerous cellular processes, including DNA damage repair, and has been shown to directly interact with IGF signaling such that variants in this pathway may modify risk of cancer in women carrying BRCA mutations." (PMID 26510816, 2015). "Moreover, the subtle nature of BRCA1 function and the well-known discrepancies between human and murine breast biology and cancer genetics may limit the utility of mouse systems in defining the function of BRCA1 in human cancer." (PMID 26379698, 2015). "Furthermore miRNA driven differences in the expression of proteins by BRCA1 vs. sporadic basal cancers may be detected via immunohistochemical staining of paraffin embedded tissue." (PMID 26152113, 2015). "Offering women BRCA1/2 gene testing is not enough to decrease cancer risk on a population basis." (PMID 26870808, 2015). "Thus no new deleterious mutations were identified in cancer cases representative of 37 French Canadian HBC/HBOC families found negative for deleterious BRCA1/ BRCA2 mutations." (PMID 25925845, 2015). "Hence stratification of basal-like cancers, based on the “BRCA1-ness” of their miRNA signature, generated from archival FFPE tissue, may be highly relevant to clinical trials investigating targeted therapies, such as PARP inhibitors." (PMID 26152113, 2015). "However, due to the small number of mutation carriers in the SEARCH dataset, it was not possible to estimate reliably the cancer risks for BRCA1 and BRCA2 mutation carriers." (PMID 26025000, 2015). "However, granulosa cells are not the site of origin of the cancers that typically develop in BRCA1 mutation carriers." (PMID 26488398, 2015). "Furthermore miRNA driven differences in the expression of proteins in BRCA1 basal cancers may be detected via immunohistochemistry." (PMID 26152113, 2015). "Thus, developing therapeutic strategies targeting RAD52 to treat PALB2, BRCA1 or BRCA2 mutant cancers might be considered." (PMID 26610585, 2015). "Although the degree of INPP4B loss that is needed for cancer cells to down-modulate ATR and BRCA1 levels and to acquire sensitivity towards PARP inhibitors still needs to be determined, we found that INPP4B loss greater than 50% in MEFs resulted in reduced levels of BRCA1, ATM and ATR proteins." (PMID 25868852, 2015). "Since tumor cells expressing high levels of BRCA1 are resistant to both IR and several classes of chemotherapeutic agents, the ablation of BRCA1 expression through Hsp90 inhibitors may restore sensitivity to anti-tumor agents, thus representing a possible cancer therapeutic strategy." (PMID 26501335, 2015). "In addition, a number of non-rare variants in genes relevant to cancer risk (e.g. in BRCA1, PALB2, BLM, and others) were detected in a significant number of individuals." (PMID 26485759, 2015). "The cancer-associated BRCT domain defects in BRCA1 that suppressed the phosphorylated RNA polymerase II (RNAP II) carboxy terminal domain (P-CTD) cleavage and lethality in yeast also suppressed the physical interaction of BRCA1 with human SPT5 in breast epithelial cells." (PMID 26418880, 2015). "Therefore, how to counsel women with family history of OvC but without BRCA1 or BRCA2 mutations has remained a major unresolved question in clinical cancer genetics." (PMID 26025000, 2015). "While loss-of-function (LoF) variants represented only a small fraction of PPVs, WGS identified additional cancer risk LoF PPVs in patients with known BRCA1/2 mutations and led to cancer risk diagnoses in 21% of non-BRCA cancer genetics patients after expanding our analysis to 3209 ClinVar genes." (PMID 26023681, 2015).
cancer (continued). "The Consortium of Investigators of Modifiers of BRCA1 and BRCA2 (CIMBA), was established in 2006 and with more than 40,000 mutation carriers currently provides the largest sample size for reliable evaluation of even modest associations between single-nucleotide polymorphisms (SNPs) and cancer risk." (PMID 24698998, 2014). "Negative mutations and/or decreased expression of the BRCA1 gene may thus activate the PI3K/AKT cancer proliferation pathway." (PMID 25426449, 2014). "Moreover, our recent study also indicated that angiotensin II type 1 receptor and epidermal growth factor receptor displayed different expression patterns in BRCA1-defective cancer cells, and confirmed that differential epigenetic regulation of transcription exist along with BRCA1 inactivation." (PMID 24675476, 2014). "However, PARP1 inhibition and the subsequent synthetic lethality can be used on other cancers that do not have mutations in BRCA1 or BRCA2 but that have a defect in the HR pathway, including mutations in ATM, Chk2, Rad51, and NBS1." (PMID 24795863, 2014). "Notably, numerous previous studies have hypothesized that BRCA1 haploinsufficiency is more likely to result in cancer, due to an extraordinary ability for clonal growth and proliferation." (PMID 24765210, 2014). "This might lead to an insufficiency of BRCA1 function in cancer cells." (PMID 24507701, 2014). "Until recently, a significant issue surrounding multigene panel testing for cancer susceptibility was that BRCA1/BRCA2 could not be included due to patents held by Myriad Genetics." (PMID 24763289, 2014). "We did not have information on genetic risk factors, such as BRCA1, that might identify clusters of cancers in high risk individuals." (PMID 24742063, 2014). "Adjuvant tamoxifen treatment may be another option to decrease the risk of cancer occurrence for individuals with BRCA1 and BRCA2 mutations who decide not to undergo preventative surgery." (PMID 24830819, 2014). "Furthermore, we have shown BRCA1 methylation in WBC of 8 out of 73 (10.9%) cancer-free women." (PMID 25403427, 2014). "Finally, we consider its significance in prevention and/or treatment of BRCA1-related cancers." (PMID 24704793, 2014). "However, all of the patients in the TCGA cohort received platinum-based chemotherapy, and the beneficial effect of a BRCA1 or BRCA2 deficiency on OS may be due to improved treatment response, or due to the less lethal potential of mBRCA-associated cancers." (PMID 24265793, 2013). "Finally, we show that 53BP1 protein expression levels was significantly correlated with molecular grouping (63.2% of HR-positive/HER2-negative vs. 47.9% of HER2-positive and 36.2% of TN tumours) and unmethylated BRCA1 promoter (53% of unmethylated vs. 27.8% of methylated cancers)." (PMID 24191908, 2013). "A significant advance in understanding the physiologic importance of the BRCA1: BARD1 interaction was the finding that the BRCA1: BARD1 heterodimer functions as an E3 ubiquitin ligase and that this ubiquitin ligase activity was abolished by cancer-associated mutations within the BRCA1 RING domain." (PMID 23802008, 2013). "Genes in this network point to reduced HR-DNA repair as the mechanism underlying cancer susceptibility, although the precise functions of associated signalling proteins (for example PTEN, CHK2, ATM and N-terminal BRCA1) that relate to cancer development are unknown." (PMID 24286369, 2013).
cancer (continued). "Nonetheless, PARP inhibition is not effective on cancers that lack the BRCA1 mutation." (PMID 24244833, 2013). "Wild-type BRCA1 but not a cancer-associated mutant significantly reduced the ROS levels." (PMID 26316936, 2012). "Failure to cleave RAD21 due to BRCA1-dependent caspase 3 inhibition may explain loss of HR repair in BRCA1 but not in BRCA2 cancers." (PMID 22537934, 2012). "This association does not apply to BRCA1 cancers, in which repair by HR between sister chromatids may be compromised by BRCA1 deficiency." (PMID 22537934, 2012). "In the majority of these cases the BRCA1 promoter is not hypermethylated suggesting that altered transcriptional regulation of the BRCA1 gene may play a causal role in this type of cancer." (PMID 21914189, 2011). "The finding of the BRCA1 mutations in individuals with no significant family history may be explained by paternal inheritance, lack of knowledge of the family cancer history or small family size." (PMID 21034437, 2010). "Thus, GEN1 might join the number of genes involved in recombinational repair such as BRCA1, BRCA2, and FANCJ/BACH, mutation of which is associated with cancer." (PMID 20661466, 2010). "The differences in pathologic features between ER+ and ER- BRCA1 cancers raise the possibility that at least some BRCA1 ER+ cancers may be 'incidental', and not caused by a complete loss of BRCA1 function in the cancer cells." (PMID 20149218, 2010). "If real, this observed excess mortality risk in the absence of any cancer suggests that BRCA1/2 mutations may exert biologic effects quite apart from their well-established influence on cancer risk." (PMID 19277124, 2009). "Furthermore, the results of the functional assays are difficult to quantify and do not necessary reflect the influence on cancer risk, since BRCA1 and BRCA2 are multifunctional." (PMID 19563646, 2009). "To examine the effect of BRCA1/2 mutations on mortality apart from their known effects on cancer risk, we studied the association between mutations and mortality in the absence of cancer in a cohort of first-degree relatives (FDR) of known BRCA1/2 mutation carriers and non-carriers." (PMID 19277124, 2009). "Hence there is strong evidence that various BRCA1 exon mutations have an effect on age-dependent expressivity that was not explained by cancer site." (PMID 19329713, 2009). "There has been no report to date on non-cancer mortality among BRCA1/2 mutation carriers." (PMID 19277124, 2009). "Physical co-deletion of BRCA1 and HER2 loci on chromosome 17q, occurring as a second somatic inactivating hit, may be at least partly responsible for the low incidence of HER2 expression oramplification in BRCA1-associated carcinomas." (PMID 19818148, 2009). "These authors showed that XIST RNA concentration on the Xi is supported by the BRCA1 protein and suggested that in BRCA1-associated carcinomas the lack of X inactivation is a consequence of BRCA1 deficiency, an assertion reiterated by the same group in a more recent study." (PMID 19440381, 2009).